WWOX (WW domain containing oxidoreductase)
Diseases named in the same sentence as WWOX in open-access papers (continued):
Sharing a sentence is not in itself a finding about the gene and the disease.
cancer (continued). "When cancer cells are transiently overexpressed with SMAD4, WWOX and HYAL-2, HA induces cell death." (PMID 35883580, 2022). "In the absence of WWOX, TGFβ/BMPs signaling was enhanced, leading to increased macrophage infiltration and enhanced cancer stemness." (PMID 36572673, 2022). "Interestingly, most of these common candidates are large cancer genes within fragile sites, such as FHIT, WWOX, CCSER1, IMMP2L, CDKN2A, and CDKN2B26,44–47." (PMID 36163358, 2022). "First, in human tumors, WWOX expression has been shown to be decreased or absent in several types of cancer." (PMID 33946771, 2021). "Additionally, Zfra4-10 or WWOX7-21 peptide increases the complex formation of WWOX with C1qBP, CD133, p21, JNK1, COX2, and p-ERK in the spleen, which correlates with cancer suppression in vivo." (PMID 32764489, 2020). "Nonetheless, UV-generated HA fragments are not effective in blocking cancer growth, suggesting that the Hyal-2/WWOX pathway is not activated in Z cells." (PMID 32764489, 2020). "Notably, Zfra4-10 or WWOX7-21 peptide induced the binding of endogenous WWOX with ERK, C1qBP, NF-κB, Iba1, p21, CD133, JNK1, COX2, Oct4, and GFAP in the spleen, brain, and/or lung, which correlates with cancer suppression." (PMID 32764489, 2020). "When mice receive Zfra peptide followed by inoculation with cancer cells, there is a significant reduction in WWOX phosphorylation at T12, S14, Y33, and Y61 in WWOX in the spleen cells in one to two months (data not shown for T12 and S14)." (PMID 32764489, 2020). "This intimate relationship between WWOX and RUNX2 was also documented in cancer." (PMID 30370248, 2018). "Conversely, WWOX-mediated cell death in A549 cancer cells was overcome by ectopic expression of VOPP1 but not VOPP1Y165A indicating that VOPP1 overexpression inhibited WWOX-dependent apoptosis." (PMID 30285739, 2018). "Upon reaching metastatic stage, cancer cells do not express WWOX due, in part, to hypermethylation at the promoter region." (PMID 30158849, 2018). "WWOX, encompassing FRA16D at 16q23.2, was cloned and mapped in early 2000 by two research groups simultaneously explaining the significance of this archetypal fragile gene in human cancer." (PMID 30370248, 2018). "This suggests that the scarcity of PTPRD and WWOX genes might have played an important role in progression of HNSCC, and could be considered as a target for cancer therapy or a biomarker in molecular pathology." (PMID 27501229, 2016). "It was determined that FRA3B (FHIT) and FRA16D (WWOX) loci rank second and third respectively, only after the CDKN2A (p16) locus, as the chromosomal sites most commonly affected by hemi- and homozygous deletions in a genome wide study of over 740 cancer lines." (PMID 24330518, 2013). "WWOX expression is inhibited or absent in many cancers such as BC." (PMID 37248434, 2023). "Interestingly, WWOX overexpression in W/C did not alter AP-2γ function, but its separate overexpression (W/K) shows an anti-cancer effect via the induction of apoptosis or inhibition of cell viability and proliferation." (PMID 34204827, 2021). "Therefore, WWOX rs73569323 SNP may affect the various miRNA binding to 3′ UTR, leading to different expression and function of WWOX in different cancer types." (PMID 34948746, 2021). "Moreover, it was shown that, using immunohistochemistry staining, WWOX is not down regulated in cancer tissue." (PMID 30619734, 2018).
cancer (continued). "The FRA16D Common Chromosomal Fragile Site (CCFS) spanning gene, WW domain containing oxidoreductase (WWOX), participates in each of these phenomena and therefore its perturbation in cancer cells presents multiple possible avenues for contributing to cancer cell biology." (PMID 26302329, 2015). "It has been proposed that in patients with WWOX↑ POLE4↑ HSF2BP↑ expression profile (who account for ~6–7% of the entire cohort), WWOX protein may not be available for its cooperating partners, which is manifested by the absence of anti-cancer activity despite a high WWOX level." (PMID 37781246, 2023). "Therefore, the altered expression of WWOX and aberrant localization should be more precisely scrutinized in these cancers; further studies on this pathway may provide a better assessment of the WWOX/VOPP1 axis in human cancers." (PMID 30285739, 2018). "It is known that WWOX and CADM1 but not CCDC80 have dense CpG islands in their promoter regions and hypermethylation at the promoter regions of WWOX and CADM1 has been reported in cancer cells." (PMID 27572307, 2016).
neurological disorders (11 papers, 2014 to 2023). "As it will be discussed in the following sections, human WWOX germline pathogenic variants have been directly implicated in complex and heterogeneous neurological disorders." (PMID 33255508, 2020). "This has led to a working hypothesis that WWOX has a central role in CNS development and homeostasis and, by extension, that its loss can lead to neurological disorders." (PMID 34831305, 2021). "Here, we review the role of WWOX in neural injury and neurological diseases, and provide perspectives for the WWOX-regulated neurodegeneration." (PMID 25537520, 2014). "In this article, we review the possible perspectives that WWOX may be involved in neural injury and its potential role in the pathogenesis of neurological diseases." (PMID 25537520, 2014). "The WW domain-containing oxidoreductase (WWOX) gene is gaining increasing attention for its possible role in both normal central nervous system (CNS) development, and its involvement in neurological diseases." (PMID 34831305, 2021).
metabolic disorders (10 papers, 2013 to 2024). "Functional deficiency or defects in the WWOX gene and protein lead to severe neural disorders, metabolic disorders, mental retardation, neurodegeneration, immune defects, stunted growth, and early death." (PMID 38542478, 2024). "This integral role of WWOX in homeostasis therefore provides a plausible explanation for metabolic disorders where genetic variation of WWOX is a risk-factor." (PMID 34210081, 2021). "The genomic region containing the WWOX gene has been identified as a genetic risk factor in each of these metabolic diseases." (PMID 34210081, 2021). "Notably, human newborns with WWOX deficiency rapidly develop severe neural diseases, metabolic disorders, retarded growth and early death." (PMID 30158849, 2018). "In conclusion, the WWOX/HIF1A axis downregulation alters glucose metabolism and probably predispose to metabolic disorders." (PMID 35328751, 2022). "Many reports also indicate the role of WWOX in different metabolic disorders including lipid metabolism, obesity, and type 2 diabetes." (PMID 30370248, 2018). "For example, when the WWOX/HIF1A axis is downregulated, glucose metabolism is altered, and the changes may allow the development of metabolic disorders." (PMID 38542478, 2024).
neurodegenerative disease (5 papers, 2013 to 2024). A disorder of the central nervous system characterized by gradual and progressive loss of neural tissue and neurologic function. "This suggests that WWOX plays a crucial role in inhibiting the aggregation of these plaque forming proteins which cause neurodegenerative diseases." (PMID 30370248, 2018).
neurodevelopmental disorder (3 papers, 2021). A behavioral and cognitive disorder with onset during the developmental period that involves impaired or aberrant development of intellectual, motor, or social functions. "Overall, it seems CNVs in the WWOX gene can result in other forms of neurodevelopmental disorders besides WOREE and SCAR12 syndromes." (PMID 34831305, 2021).
infection (2 papers, 2004 to 2015). The state of being infected such as from the introduction of a foreign agent such as serum, vaccine, antigenic substance or organism.
autosomal recessive disease (1 paper, 2021). Autosomal recessive form of disease. "The germline inactivation of the WWOX gene through homologous deletion can lead to human autosomal recessive diseases, such as the WWOX-related epileptic encephalopathy syndrome." (PMID 34948746, 2021).
colon (1 paper, 2014). "Our experiments seem to confirm and delineate further behavioural differences between HT29 and SW480 and indicate the diverse effects of WWOX functioning in colon cancerogenesis." (PMID 24938873, 2014). "The study investigated the role of the WWOX gene in colon cancerogenesis." (PMID 24938873, 2014).
WWOX also shares sentences with these, for which no sentence is quoted: cerebellar ataxia (5 papers); infantile epileptic encephalopathy (4); lymphoma (4); retinal degeneration (4); autism spectrum disorder (3); early infantile epileptic encephalopathy (3); esophageal squamous cell carcinoma (3); gastric adenocarcinoma (3); melanoma (3); B cell lymphomas (2); developmental and epileptic encephalopathy 28 (2); dwarfism (2); esophageal cancer (2); Insulin resistance (2); renal cell carcinoma (2); adenocarcinoma (1); Anaplastic Carcinoma (1); Anxiety (1); arrhythmogenic right ventricular cardiomyopathy (1); attention deficit-hyperactivity disorder (1); autoimmune disease (1); Barrett esophagus (1); basal-like breast carcinoma (1); benign ovarian tumors (1); bladder (1); cardiac diseases (1); cardiovascular diseases (1); cerebellar disorder (1); cholangiocarcinoma (1); clear cell carcinoma (1).
A further 44 diseases each share a sentence with WWOX in 1 paper.